MMP2 (matrix metallopeptidase 2)
Diseases named in the same sentence as MMP2 in open-access papers (continued):
Sharing a sentence is not in itself a finding about the gene and the disease.
glioblastoma (224 papers, 2006 to 2026). The most malignant astrocytic tumor (WHO grade IV). "CLTX-CAR T cells employ the chlorotoxin peptide as a tumor recognition domain, redirecting T cell cytotoxicity against glioblastoma cells through MMP-2–associated binding." (PMID 41155199, 2025). "This was previously demonstrated in glioblastoma, where AP-2α loss correlated with MMP2 overexpression hence invasion." (PMID 33718178, 2021). "Glioblastoma growth, hypoxia, and angiogenesis have been shown to be associated with mesenchymal marker expression including MMPs, and more especially MMP-2 during blood vessel reorganization and MMP-9 during invasion." (PMID 33937253, 2021). "In glioblastoma, high MMP-2 was associated with poorer prognosis in patients who survived longer than 8.5 months independent of age and gender (HR 2.27; 95% CI 1.07–4.81; p = 0.033)." (PMID 28234925, 2017). "EGF through its receptor (EGFR), which is frequently overexpressed in glioblastomas, promotes the transcription of genes associated with the extracellular matrix proteolysis such as matrix metalloproteases 2 and 9 (MMP-2 and 9)." (PMID 28168193, 2017). "Previous studies have shown that MMP2 expression deficiency decreases corneal angiogenesis, and MMP2−/− had increased survival times, vessel density, invasive phenotypes and migration along blood vessels in the brain parenchyma in a glioblastoma model." (PMID 25013467, 2014). "In view of our data, it is reasonable to infer that the inhibitory effect of α-H on glioblastoma cell migration and invasion may be associated to MMP-2 and MMP-9 downregulation." (PMID 31551765, 2019). "Thus, the inhibitory effects of SH on glioblastoma cell metastasis are associated with reduced MMP-2/-9 expression." (PMID 29538296, 2018). "In conclusion, this study indicates that MMP-2 is associated with aggressiveness in astrocytomas and may hold an unfavorable prognostic value in patients with glioblastoma." (PMID 28234925, 2017). "Thus, the reduced MMP2 activity may contribute to the decrease of migration and invasion caused by pioglitazone, rosiglitazone and WY‐14643 in the glioblastoma cells under in vitro and in vivo conditions." (PMID 39636301, 2024). "Astrocytes then become activated and start secreting elevated amounts of chemokines (e.g. IL-6), enhancing glioblastoma cell invasion and tissue infiltration by increased production MMPs, especially MMP-2 and MMP-9." (PMID 41208963, 2025). "CLTX was initially characterized based on its inhibition of glioma-specific chloride ion channels (GCC), however recent studies identified MMP-2 as the principal receptor for CLTX on the surface of glioblastoma cells." (PMID 41208963, 2025). "Studies in glioblastoma have demonstrated that EGFRvIII expression directly regulates the release of MMP2 and MMP9, leading to ECM breakdown and enhanced tumor invasiveness." (PMID 40472740, 2025). "The bioresponsive material selectively inhibits MMP‐2 versus MMP‐9 in glioblastoma microenvironment." (PMID 40556034, 2025). "Inhibition of MMP-2 enzymatic activity and inhibition of its glioblastoma cell migration by peptides were also assessed through an MMP-2 inhibition assay and a wound-healing scratch assay." (PMID 40791509, 2025). "Glioblastoma aggressively invades surrounding tissue by expressing matrix metalloproteinase-2 (MMP-2)." (PMID 40791509, 2025). "As of 2025, nanoparticle-based delivery systems are being explored to improve MMP inhibitor efficacy, particularly in glioblastoma, where MMP-2 and MMP-9 drive ECM degradation and tumor invasion." (PMID 41303525, 2025). "Nuclear accumulation of β-catenin in glioblastoma cells led to the upregulation of transcriptional targets including Oct-4, MMP-2, Nanog and c-Myc." (PMID 40429889, 2025). "MMP-2 expression is increased in glioblastoma TME, contributing significantly to the tumor invasiveness." (PMID 41208963, 2025).
glioblastoma (continued). "Its ability to target ClC-3 channels and MMP-2 in glioblastoma and breast cancer positions it as a promising candidate for further preclinical and clinical evaluation, particularly in the development of tumor-specific diagnostic and therapeutic agents." (PMID 41155199, 2025). "The observation that the LN229 line has a greater ability to secrete MMP-2 compared to the LN18 line indicates that glioblastomas of different origins have various abilities to model the tissues surrounding the tumor." (PMID 40141020, 2025). "This ConA-mediated activation of MMP-2 was indeed observed by zymography in the U87 glioblastoma cell model, and α-TGG inhibited this activation." (PMID 40248812, 2025). "They observed elevated expression of MMP9 and MMP2 in anaplastic astrocytomas, oligodendrogliomas, and glioblastomas compared to meningiomas and other benign tumors, indicating a direct relation between MMP9 and MMP2 expression and malignant behavior." (PMID 38474106, 2024). "We examined the effects of sodium fluoride (NaF) exposure on the migratory and invasive abilities of the U-87 human glioblastoma cell line, assessing levels of metalloproteinases MMP-2 and MMP-9 secreted by these cells." (PMID 39684484, 2024). "Treatment with chrysomycin-A significantly inhibited the growth of glioblastoma cells and weakened the ability of cell migration and invasion by downregulating the expression of slug, MMP-2, and MMP-9." (PMID 38396785, 2024). "For instance, it was demonstrated that FLNC enhances the aggressiveness of glioblastoma cells by inducing MMP2 activation, leading to poor prognosis." (PMID 38363409, 2024). "Formate has also been shown to favour migration of glioblastoma cells lines through upregulation of matrix metalloproteinase 2 (MMP2)." (PMID 38698089, 2024). "A similar experiment, but on glioblastoma-initiating cells (GICs), revealed reduced MMP-2 activity and protein expression, probably due to the downregulation of the NF-κB and PI3 K/Akt/mTOR pathways." (PMID 39335164, 2024). "Gaining inspiration from the previous outcomes, a phase I clinical study is presently evaluating the therapeutic effect of CLTX CAR T cells on patients with recurrent or progressive MMP2-positive glioblastoma." (PMID 36721153, 2023). "Behavior of glioblastoma cells, including their motility, and expression of invasion-promoting genes such as matrix metalloprotease-2 (MMP2), are strongly influenced by normal cells found in the brain parenchyma." (PMID 36970613, 2023). "Supporting these outcomes, in-vitro studies showed the capability of CAR to decrease the MMP-9, MMP-2, and ROS in human glioblastoma and human mesenchymal stromal." (PMID 37666857, 2023). "Chr-A treatment significantly inhibited the growth of glioblastoma cells and weakened the ability of cell migration and invasion by down regulating the expression of slug, MMP2 and MMP9." (PMID 36234681, 2022). "Several studies have demonstrated that alterations in NO production regulates ATF3 expression and consequently interferes in MMP-2 expression in endothelial cells, glioblastoma, and mouse brain endothelial cells." (PMID 35137850, 2022). "At 10 μM, it can suppress the growth and migration of glioblastoma cells by suppressing Erk1/2, Akt, cyclin D1, MMP2/9, and fibronection activation and activating p38 and p27 expressions." (PMID 36307808, 2022). "AuNP activated by MMP-2 have also been utilized to characterize protease activity and exhibit retention at the cleavage site in a glioblastoma mouse model, which like OvCa upregulates MMP-2." (PMID 36077371, 2022). "Bevacizumab treatment led to increased expression and enzymatic activity of MMP-2 and MMP-9, common metalloproteinases associated with neovascularization of tumors, in glioblastoma cells both in vitro and in vivo." (PMID 33804681, 2021). "ERK1/2 blocking inhibits MMP-2-mediated cell motility and further enhances the anti-invasive ability of tricetin in glioblastoma multiforme cells." (PMID 34445346, 2021).
glioblastoma (continued). "In glioblastoma, MMP2 serves as an important MMP to degrade the extracellular matrix (ECM) subsequently enabling the invasive properties of glioblastoma." (PMID 32299465, 2020). "The scorpiontoxins AaCTx and ClTx target the matrix metalloproteinase-2 (MMP-2) inhibiting the glioblastoma cell invasion." (PMID 32429050, 2020). "It is widely accepted that MMP2 expression is correlated with the expression of Ang2 in glioblastoma." (PMID 33473259, 2020). "Selective inhibition of MMP2 at invasive front can hampered the Ang2 induced activities in glioblastoma." (PMID 33473259, 2020). "As there were a series of downstream molecules of this pathway involved in proliferation, apoptosis, migration, and invasion of glioblastoma, we examined some of the downstream molecules, including: Cyclin D1, p21, Bcl-2, Bax, MMP-2, and MMP-9." (PMID 32596388, 2020). "Recently, first studies confirmed a common interaction site of HSP27 in glioblastoma for both MMP2 and MMP9." (PMID 33287446, 2020). "To further understand the anti-invasive activity of CTR-GNPs on human U87 glioblastoma cells, we used gelatinase zymography to confirm the enzymatic activity of MMP-2/-9." (PMID 32074974, 2020). "This study presented anti-metastatic effects of ATX against A172 human glioblastoma cells by inhibiting migration and invasion abilities with reducing MMP-2 and MMP-9 expressions as target molecules." (PMID 32711429, 2020). "MMP2 is secreted by glioblastoma cells in a pro-form (pro-MMP2) which needs to be cleaved by Mmp14 (MT1-MMP) to be active." (PMID 32299465, 2020). "Baumann previously reported that lactic acid promoted the invasion and metastasis of malignant glioblastoma by inducing the expression of matrix metalloproteinase 2 (MMP-2)." (PMID 33178600, 2020). "Recently, scientists also found that Id4 is involved in the suppression of matrix metalloproteinase 2 (MMP2)-mediated cell invasion in glioblastoma and also in the modulation of miR-342-regulated breast cancer type 1 susceptibility protein (BRCA1) expression." (PMID 31847356, 2019). "Naringin inhibits the invasion and migration of human glioblastoma cell via down-regulation of MMP-2/-9 expression and inactivation of p38 signaling pathway." (PMID 31632484, 2019). "We demonstrate that RNA isolated from pseudopodia of hGCs contains migration-specific transcripts including Cdc42, Cofilin-1, Ezrin, Ilk, Limk, STAT3, MMP2, and Itgb1, recently described as part of intracellular pathways related to glioblastoma migration." (PMID 30353164, 2019). "Specifically, MMP-2/-9 are known as important enzymes in invasion, and their levels increase during glioblastoma progression." (PMID 29538296, 2018). "Some studies also indicated that MMP-2 was correlated with glioblastoma invasion, angiogenesis, metastasis, and relapse." (PMID 29423667, 2018). "As our results showed, PF exerted anti-migration and invasion via inhibiting the EMT and MMP2/9, which reflects the dual suppressive effects of PF in glioblastoma." (PMID 29423667, 2018). "Tissue samples from 89 patients diagnosed with diffuse astrocytoma, anaplastic astrocytoma and glioblastoma were stained immunohistochemically using a monoclonal MMP-2 antibody." (PMID 28234925, 2017). "In conclusion, we have presented the first evidence linking SH3GL2 to malignant behaviours of human glioblastoma through STAT3/MMP2 pathway." (PMID 28470949, 2017). "At human glioblastoma (T-98G) cells, MMP-2 and MMP-9 expression decreased with increased concentration of treatment, with the nutrient mixture being most effective, followed by green tea extract and then EGCG." (PMID 29181405, 2017). "MMP-2 also facilitates cancer cell invasion in glioblastoma multiforme, a brain tumour in which TGFβ1 is highly expressed." (PMID 26867675, 2016). "Our previous study with other bee products proved that beebread and various honeys also inhibited the secretion of MMP9 and MMP2 in glioblastoma cells." (PMID 27647142, 2016).
glioblastoma (continued). "The inhibition of MMP-2 activity or downregulation of MMP-2 protein levels inhibits migration and invasion of glioblastoma cell lines in vitro and in vivo." (PMID 25965832, 2015). "Adenovirus-mediated transfer of siRNA against MMP-2 mRNA results in impaired invasion and tumor-induced angiogenesis, induces apoptosis in vitro and inhibits tumor growth in vivo in glioblastoma." (PMID 24715095, 2014). "Our previous results showed that transient ERK1/2 activation had positive correlation to the expression and activity of downstream invasion-related protein MMP-2 in human glioblastoma U87MG cells." (PMID 24587385, 2014). "The role of miR-149 was explored in glioblastoma where it was found to inhibit the expression of MMP-2, p-AKT1, proliferating cell nuclear antigen (PCNA), cyclin D1, as well as proliferation and invasion in U251 cells." (PMID 24670365, 2014). "In conclusion, here we revealed that SFN activated ERK1/2 in a sustained way, further downregulated MMP-2 and upregulated CD44v6, resulting in the inhibition of invasion in glioblastoma cells." (PMID 24587385, 2014). "Human glioblastoma samples express elevated levels of MMP-2 compared with low grade brain tumors and normal brain tissues." (PMID 24587385, 2014). "MMP2 was reported to be highly expressed by endothelial cells in different tumors including human glioblastomas and its activation is contributed by H2O2, which is found highly elevated in liver of DL mice." (PMID 24932681, 2014). "Anosmin-1 enhanced glioblastoma cell motility and colocalized with the leading edge of migrating cells while enhancing uPA and MMP2/9 activities." (PMID 24189182, 2014). "In particular, MMP-2 is highly expressed in glioblastoma and its expression increases with tumor progression at both the mRNA and protein levels." (PMID 24587385, 2014). "Upregulation of MMP-2 subsequent to different irradiation conditions was observed in different tumor types (e.g., pancreatic cancer, glioblastoma, colorectal cancer and fibrosarcoma), leading to enhanced cell invasion." (PMID 23381805, 2013). "Matrix metalloproteinase-2 (72 kDa, MMP-2, also termed gelatinase A) and MMP-9 (94 kDa, also termed gelatinase B) are proteolytic collagenases strongly associated with glioblastoma growth and invasion." (PMID 23594434, 2013). "The knockdown of CD155/PVR/Necl-5 in glioblastoma cells also decreased the matrix metalloproteinase-2 (MMP-2) expression and activity and resulted in markedly decreased cell invasion." (PMID 23833639, 2013). "PAX6 has been described as a tumor suppressor, suppressing invasiveness of glioblastoma cells and MMP2 expression, both of which are hallmarks of EMT." (PMID 24283570, 2013). "Glioblastomas are highly hypoxic and hypoxia upregulates MMP-2 mRNA expression in U87, U251, U373 and LN18 glioblastoma cell-lines by activation of the HIF-1 transcription factor, thereby enhancing their invasive potential." (PMID 21067565, 2010). "Given the capacity of α-TGG to inhibit ConA-mediated pro-MMP-2 activation, we questioned whether any other intracellular signaling which triggers inflammation may be affected in U87 glioblastoma cells." (PMID 40248812, 2025). "Additionally, formate supplementation can increase the expression of genes implicated in lipid metabolism, resulting in reduced invasion of glioblastoma cells and decreased levels of MMP2 in response to fatty acid synthesis inhibitors." (PMID 38698089, 2024). "Furthermore, after GOLPH3 knock down in glioblastoma cell line, they observed that these cells expressed higher E-cadherin and lower MMP2." (PMID 38372877, 2024). "In U87 glioblastoma cells, EGCG inhibited ConA-mediated MT1-MMP induction and proMMP2 activation which is likely to be caused by the binding interaction of EGCG with MT1-MMP and MMP2." (PMID 36677584, 2023).
glioblastoma (continued). "These flavonoids have been found to suppress cell migration by modifying the cell surface, reducing filopodia-like structures, downregulating MMP2, and activating fibronectin (both intra- and extra-cellular) and laminin (intracellular) in human glioblastoma cells." (PMID 36307808, 2022). "Moreover, in U87MG glioblastoma cells, treatment with Iso determined an intensification of the proteolytic activity of the metalloproteases after 24 h of treatment; the levels of MMP-2 were reduced with an increase of MMP-9 form." (PMID 36500428, 2022). "In addition, SIN can effectively reduce the metastases of mankind glioblastoma via inhibiting the MMP2/9 signaling pathway." (PMID 35860597, 2022). "NFE2L2 is involved in mediating TMZ glioblastoma resistance via MMP-2." (PMID 36231068, 2022). "Step 2, the enzymatically cleavable linkers (matrix metalloproteinase 2 [MMP-2] responsive peptides) that are attached to the cell penetration-enhancing R8 peptide in the middle shell ensure the glioblastoma cell internalization following MMP-2 cleavage in the tumor microenvironment." (PMID 35975300, 2022). "In addition, cadherin-5, VEGF, IGFBP2, and MMP2 (MMP2 was detected in two glioblastoma cyst fluid samples are involved in the generation of vasculogenic mimicry in glioblastomas." (PMID 35659255, 2022). "FAK signalling regulates MMP‐2 expression and the migration and invasion of human glioblastomas." (PMID 34528373, 2021). "Id4 is involved in suppressing the MMP2-mediated cell invasion in glioblastoma." (PMID 33936204, 2021). "In this study, HOXA-AS2 was found to be overexpressed in glioblastoma tissues and cells, to inhibit cell apoptosis, and to enhance cell proliferation, migration, invasion and the protein expression of Twist, Slug, Vimentin and MMP-2." (PMID 33430870, 2021). "Similarly, amentoflavone was found to inhibit metastasis down-regulation of MMP-2 and -9 and to block glioblastoma and osteosarcoma tumor progression through via suppression of the ERK/NFκB signaling pathway, with a down-regulation of MMP-2 and -9." (PMID 33534099, 2021). "Taken together, we speculated that HMGN5 in glioblastoma cells could regulate Bcl-2, Bax, Cyclin D1, p21, MMP-2, and MMP-9 to play an oncogenic role partly via the PI3K/AKT pathway." (PMID 32596388, 2020). "Glioblastoma cells promote their mobility, invasion, and metastasis through degradation of the extracellular matrix (ECM) mediated by tumor-associated matrix metalloproteinases (MMPs), such as MMP-2 and MMP-9." (PMID 32074974, 2020). "Furthermore, fucoxanthin treatment suppressed MMP-2, -9, and uPA by reducing the phosphorylation of p38 in U87 and U251 human glioblastoma cells." (PMID 33321708, 2020). "Overexpression of MMP-2 or MMP-9 strengthens EMT process in glioblastoma." (PMID 29423667, 2018). "Moreover, cell invasion and expression of the matrix metalloproteinase genes MMP1 and MMP2 are significantly enhanced by CAV1 in glioblastoma cells." (PMID 29340103, 2017). "Moreover, numerous studies shown that downregulation of MMP-2 expressions contribute to the inhibition of metastasis in glioblastoma cells." (PMID 29285298, 2017). "After shikonin treatment on human glioblastoma cells, MMP-2, MMP-9, p-AKT, and p-PI3K decreased." (PMID 29181405, 2017). "Moreover, the inhibition of AEG-1 expression significantly induces the apoptosis and suppresses the invasive ability of human malignant glioblastoma U251 and U87 cells by modulating MMP-2, MMP-9 activity and EMT characteristics." (PMID 27251589, 2016). "Calpain-2 can also increase MMP2 activity to promote glioblastoma cell invasion." (PMID 27453531, 2016). "Furthermore, calpain-2 has been reported to increase MMP2 activity, resulting in enhanced glioblastoma cell invasion." (PMID 27453531, 2016). "MMP-2 expression decreased in glioblastoma cells by treatment with carvacrol." (PMID 27803760, 2016).